PDCD1 (programmed cell death 1)
Diseases named in the same sentence as PDCD1 in open-access papers (continued):
Sharing a sentence is not in itself a finding about the gene and the disease.
tumor (continued). "Numerous transcripts related to immunological checkpoints, including SIGLEC15, PDCD1LG2 (PD-L2), TIGIT, PDCD1 (PD-1), CD274 (PD-L1), CTLA4, LAG3, and HAVCR2 (TIM3), are integral to tumor immune evasion mechanisms." (PMID 41194934, 2025). "Spatial depletion of Streptococcus and Acetivibrio in tumor niches disrupts butyrate-histone deacetylase (HDAC) signaling, leading to programmed cell death 1 (PDCD1) hyperacetylation and CD8+ T-cell exhaustion." (PMID 41438381, 2025). "Tumor metabolite lactate promotes tumor growth by regulating MOESIN lactylation in Treg cells, and the LDH inhibitor GSK2837808A combined with anti-programmed cell death-1 (anti-PD-1) has a stronger anti-tumor effect than by anti-PD-1 alone." (PMID 40584617, 2025). "Other upregulated genes included NR3C1, NMB, and COTL1, which are coordinately expressed with PDCD1, CXCL13, and ENTPD1 by tumor infiltrating CD4+ T cells." (PMID 40956619, 2025). "The results showed that the removal of PDCD1 and CD96 significantly contributes to the suppression of tumor growth, leading to complete remission." (PMID 41369346, 2025). "CD4 + ICOS + PDCD1+ (PD-1) T-cells, resembling T follicular helper (Tfh) cells were more common in HPV+ve tumours, as were CD4 + naïve-like T-cell clusters and KIT + NK-cells." (PMID 39757146, 2025). "In our study, we found that CD4 Treg, CD8-Tem-PDCD-1, and CD8-Temra levels gradually increased during tumor progression." (PMID 39354287, 2025). "CXCL12 correlated with CD274 (R = 0.369) and PDCD1 (R = 0.288); CXCR4 correlated with CD274 (R = 0.579) and PDCD1 (R = 0.520), suggesting their roles in regulating immune checkpoints and tumor immune escape." (PMID 41142306, 2025). "PD-1 (also called PDCD1 or CD279) is expressed on activated T cells, while its major ligand, PD-L1, is expressed on various cells, including tumour cells." (PMID 41523470, 2025). "Further database analysis (TIMER2.0) showed that PDCD1 gene expression was positively correlated with the levels of immunosuppressive genes (CD274, PDCD1LG2, TGFB1, and IL10) in most human tumor types." (PMID 38441961, 2024). "Inhibitors of programmed cell death-1 (PD-1)/programmed cell death ligand-1 (PD-L1) and cytotoxic T lymphocyte antigen 4 (CTLA-4) activate tumor-specific T cells and provide therapeutic efficacy." (PMID 39235457, 2024). "PDCD1 and TCF7 were overrepresented in mTLSs as compared to eTLSs and nTLS areas in 3 independent tumor samples, with a similar but subsignificant trend for HAVRC2." (PMID 38514660, 2024). "Targeting the transmembrane protein Programmed cell death 1 (PD1) on cytotoxic T cells, PD1 inhibitors induce an antitumoral immune response by promoting T cell proliferation and infiltration into the tumor." (PMID 38969911, 2024). "CD8-positive tumor-infiltrating lymphocytes (TILs), which are representative markers of the tumor microenvironment (TME), also serve as predictors of anti-programmed cell death-1 (PD-1) treatment in NSCLC." (PMID 38344209, 2024). "By investigating LR interactions involving immunomodulatory targets (CRI-iAtlas), we identified interactions between CD274 (PD-L1), its receptor PDCD1 (PD-1) and its costimulator CD80 (B7-1) exclusively in RP-like tumours." (PMID 37758326, 2024). "Similar to PDCD1 and CTLA4, which were scattered across the tumor region with evident T cell aggregation, CXCL13-CXCR5 had a similar spatial distribution." (PMID 39256364, 2024). "PDCD1 and CTLA4 were scattered sporadically in the tumor region with T cell aggregation, and they were more widely distributed in the CA group than the NC group." (PMID 39256364, 2024). "The Tumor Immune Estimation Resource (TIMER) database was further employed to explore the relationship between TGFBR1 and PDCD1 gene expression in various human tumors." (PMID 38441961, 2024). "By blocking the release of TGF-β1 from UPP1-overexpressing tumor cells using TGF-β1 neutralizing antibodies, we observed a marked decrease in the LAG3 + PDCD1+ exhausted T cell population." (PMID 38331898, 2024).
tumor (continued). "The results demonstrated a positive correlation between FANCD2 and immune checkpoints in most tumor tissues, including CTLA4, HAVCR2, LAG3, PDCD1, PDCD1LG2, SIGLEC15, TIGIT, and particularly CD274." (PMID 38443946, 2024). "While in tumor‐core tissues, canonical CD8+T cells with GZMK/B/A and exhausted molecules (TOX and PDCD1) dominate, which is completely different from the naïve and low‐cytotoxic/exhausted states of CD8+T cells in the leading‐edge area." (PMID 39716897, 2024). "Programmed cell death protein 1 (PDCD1, PD-1, CD279) and programmed cell death ligand 1 (PD-L1, CD274/B7-H1) are regarded as key targets for anti-tumor immunotherapy currently." (PMID 39076970, 2024). "Overall, it included more than 12000 TCGA samples and established the relationships between PDCD1/LAG3 gene expression with immune cell infiltration and an extensive number of biomarkers within the tumor-immune infiltrate." (PMID 39030301, 2024). "CSC-derived EVs are likely to interact with immune cells enriched in the CSC niche, including MHC-II expressing macrophages and programmed cell death 1 (PD1) positive T cells, potentially promoting tumor progression through immunosuppression." (PMID 38962016, 2024). "The transcriptomic profile that we found in tumour-reactive CD137+ CD8+ T cells suggested an exhausted/activated-like phenotype with increased expression of TNFRSF9, LAG3, PDCD1, TIGIT and HLA-DPA1/HLA-DQA1." (PMID 38986249, 2024). "Notably, cytotoxic T-lymphocyte-associated protein 4 (CTLA4) and PD-1 (PDCD1) genes serve as exemplars of immune checkpoint genes, and the application of antibody therapy to inhibit the CTLA4 or PD-1 checkpoints has been shown to unleash T-cells for tumor eradication." (PMID 38164277, 2024). "The GEPIA database compared PDCD1 and LAG3 mRNA expression between AML tumor samples and healthy control samples from TCGA." (PMID 38792904, 2024). "To assess the potential tumor suppressor role of APOB in HCC, we employed the Spearman correlation coefficient to evaluate the relationship between APOB and CD274, PDCD1, and CTLA4." (PMID 38310202, 2024). "Researchers have successfully generated TRAC, B2M, and PDCD1 multiplex knockout CAR-T cells targeting CD19 or prostate stem cell antigen (PSCA), exhibiting reduced alloreactivity coupled with enhanced anti-tumor activity." (PMID 38816881, 2024). "Next, after 2 weeks of tumor implantation using A20 cells, mice were randomized and allocated to four treatment groups in which PBS and L. braziliensis was combined with anti-programmed cell death-1 (PD-1) and isotype control antibody regimens." (PMID 38457336, 2024). "Most immune checkpoints, including PD‐L1 and Programmed cell death 1 (PDCD1), involved in immune escape of tumor cells, were also highly expressed in the high HEC1 expression group." (PMID 39021287, 2024). "These tumor-specific upregulated genes included inhibitory receptors, such as ENTPD-1 49 and PDCD1, as well as effector molecules, such as GZMK and IFNG, all involved in antitumor activity." (PMID 38948071, 2024). "We found that it was correlated with tumor immunotherapy targets BTLA, CTLA4, HAVCR2, LAG3, PDCD1, and TIGIT in HNSC; ICOS were all significantly correlated." (PMID 39483471, 2024). "Flow cytometry was performed to confirm the MS results on several critical markers of tumor immune responses including CD25 (IL2RA), CD5, CD137 (TNFRSF9), ICOS, PD1 (PDCD1), CTLA4, and CD62L (SELL)." (PMID 38242867, 2024). "Although LAG-3 B cells comprised a minor portion of total tumor-infiltrating B cells (49 cells), evaluating other cellular markers, we observed co-expression of IGHD and PDCD1 alongside LAG-3." (PMID 38773133, 2024). "Dysfunctional T cell subgroups (characterised by T cell exhaustion), immunosuppressive myeloid subgroups marked by SPP1, PDCD1, or TERM2, and fibroblasts have been observed at the tumour boundary." (PMID 39350478, 2024).
tumor (continued). "CBLB was brought up among more than 100 ubiquitin-related target genes in lymphoid infiltration, and it was found to be among the top E3 ubiquitin ligases co-expressed with PDCD1 and LAG3 in the tumor microenvironment (Dataset EV3)." (PMID 39030301, 2024). "Specifically, the expression levels of immune checkpoint genes CTLA4 and PDCD1 (the gene coding for PD-1) were significantly increased in the low PIDG score group, suggesting an active immune state and a stronger anti-tumor immune response." (PMID 38136994, 2023). "The relationship between PIMREG and immune checkpoints, including PD1 (PDCD1), PD1-L1 (CD274), and CTLA-4, which play a crucial role in tumor immune evasion, was assessed." (PMID 37483962, 2023). "Knockout or silencing of PDCD1 by CRISPR/Cas9 or short hairpin RNA (shRNA) has been shown to increase anti-tumor effects." (PMID 37596653, 2023). "In addition to TKI, ICIs such as programmed cell death 1 (PD-1)/ programmed cell death ligand 1 (PD-L1) inhibitor, pembrolizumab, atezolizumab, nivolumab, sintilimab, camrelizumab, tislelizumab and durvalumab, have revolutionized malignancy tumor therapy in recent years." (PMID 37844117, 2023). "The relationship between the expression levels of CD274, TIGIT, PDCD1, CTLA4 and LAG3 in tumor tissues of normal and LUAD patients and the relationship between each gene and the survival rate of LUAD patients." (PMID 36959799, 2023). "Furthermore, increasing tumor mutation burden, usually defined as the number of nonsynonymous mutations per megabase of sequenced DNA, is also a predictive biomarker for better response to programmed cell death 1 (PD-1) blockade and improved clinical outcomes." (PMID 37143088, 2023). "Single-cell RNA-seq of PyMT tumor CD8+ T cells revealed unique signatures for early effectors (Il7r, Tcf7), exhausted (Pdcd1, Tox), and ILTCKs (GzmB, Klrb1c, Fcer1g)." (PMID 37892995, 2023). "All immune checkpoints were significantly different between the normal and tumor groups (P < 0.05), in which PDCD1, CTLA4, and HAVCR2 were highly expressed in tumor tissues, while CD274, LAG3, and PDCD1LG2 were highly expressed in normal tissues." (PMID 37872211, 2023). "Since LAG3, PDCD1 and TIGIT have long been identified as key immune checkpoints in ccRCC, their blockade has demonstrated satisfactory anti-tumor efficacy in preclinical and clinical studies." (PMID 37679715, 2023). "Here, by Cox modeling, we develop IRS—which combines TMB with CD274, PDCD1, ADAM12 and TOP2A quantitative expression—to predict pembrolizumab rwPFS (648 patients; 26 tumor types; IRS-High or -Low groups)." (PMID 36750617, 2023). "PDCD-1 and LAG3, two immunosuppressive molecules, play important roles in tumor-cell-mediated immune escape." (PMID 37131179, 2023). "mAbs blocking the PDCD1/CD274 checkpoints inhibit the co-inhibitory signal on Teff cells and promote cytotoxic activity against tumor cells." (PMID 37215135, 2023). "TIM-3 expression was correlated with clinicopathological parameters including tumor-infiltrating lymphocyte (TIL) counts, programmed cell death 1 (PD-1) and programmed cell death ligand 1 (PDL-1) expression in patients with HR-STS." (PMID 37345075, 2023). "To further confirm the effect of Cbx4 on Pdcd1 promoter region in tumor, we sorted out CD3+ T cells in draining lymph nodes from MC38 tumor‐bearing mice and checked their H2AK119ub1 and H3K27me3 deposition in the Pdcd1 promoter region." (PMID 37691307, 2023). "Our results showed that tumor targeting-related immune checkpoint genes such as CD274 (p = 0.0137), TGFB1 (p = 0.0175), PDCD1 (p < 0.001), CTLA4 (p < 0.001), and LAG3 (p < 0.001) were significantly associated with APOC1." (PMID 36969562, 2023). "The associations of mRNA expression between CRABP2 and three immune checkpoint molecules (PDCD1, CD274 and CTLA4) were examined in 33 different tumor types from the TCGA database using the TIMER2.0 and Xiantao tools." (PMID 38186580, 2023).
tumor (continued). "Immune checkpoint inhibitors (ICIs), for example, inhibitors targeting programmed cell death 1 (PDCD1) protein and its ligand protein of PD-L1, have made a significant contribution to tumor immunotherapy." (PMID 36961395, 2023). "To investigate the immune profiles of c-Scorehi tumors across the 25 TCGA tumor types, we evaluated immunomodulatory genes involved in immune checkpoint blockade response, (CD274 [PD-L1], PDCD1 [PD-1], HAVCR2 [TIM3], LAG3, TIGIT, CTLA4, and FASLG)." (PMID 37558751, 2023). "Exhausted CD8+ T-cells (PDCD1+CTLA4+) and Tregs (TIGIT+CTLA4+) were abundant in the tumor and expressed the inhibitory marker LAYLIN (LAYN)." (PMID 37511228, 2023). "Tumor-reactive CD8+ T cells generally showed a methylation pattern like exhausted cells, as exhausted signature genes (PDCD1 and CTLA4) were found to be demethylated the same as how in naïve T cells they were found to be hypermethylated." (PMID 36672677, 2023). "Our analysis of immune cell subtypes and immune checkpoint gene expression revealed that the PTMC-Inf tumor shares the same characteristics (more infiltrating CD4 + and CD8 + T cells, and high expression of PDL1, PDCD1, and CTLA4)." (PMID 36941725, 2023). "Notable, the expression of multiple immune checkpoints in the tumor issue is significantly high such as PDCD1, CD274, and TIM3, which suggests Cluster B is a typical immune‐inflamed tumor." (PMID 35801342, 2023). "Programmed death-1 (PDCD-1) and lymphocyte activating 3 (LAG3), two important immunosuppressive molecules, play crucial roles in immune escape of tumor cells." (PMID 37131179, 2023). "MIAT was mainly distributed in tumor, and enriched in FOXP3 + CD4 + T cells and PDCD1 + CD8+, GZMK + CD8 + T cells through single cell sequencing analysis, indicating that it palyed an important role in immune escape of HCC." (PMID 36810034, 2023). "The major immune checkpoints include PDCD-1, CD274 (also known as PD-L1), CTLA-4, HAVCR2 (also called TIM-3), LAG-3 and TIGIT which are responsible for tumor immune escape." (PMID 37810780, 2023). "For exhaustion related to the CD274/PDCD1 axis, this is clearly justified because IFNG can induce upregulation of CD274 on tumor cells." (PMID 37182110, 2023). "PD1 (PDCD1), PD-L1 (CD274), CTLA-4, and TIM-3 (HAVCR2) are important immune checkpoints responsible for tumor immune escape." (PMID 36714030, 2023). "Investigators have also detected significantly higher expression of the immune checkpoint genes CTLA4, PDCD1, LAG3 and ICOS and PD-L1 protein expression in high-grade compared with low-grade tumours." (PMID 36928373, 2023). "The PD1 (PDCD1)-PD-L1 (CD274) receptor-ligand pairs were identified between PD1 + T cells and PD-L1 + tumor cells." (PMID 36944944, 2023). "PDCD1, also known as PD1, were known as programmed death ligands and receptors, respectively, and its combination with PD-L1 allows tumor cells to evade the body's immune surveillance." (PMID 37342680, 2022). "It has been shown that deletion of T Cell Receptor Alpha Constant (TRAC), B2M, and PDCD1 in universal EGFRvIII and CD19-CAR-T cells enhanced their anti-tumor responses, respectively, against both solid and hematologic malignancies (glioblastoma and leukemia)." (PMID 36419058, 2022). "TIM-3, which is expressed on the surface of CD4+ and CD8+ T cells, is involved in enforcing T-cell exhaustion by interaction with tumour cells; therefore, TIM-3 is considered as an exhaustion marker of lymphocytes similar to programmed cell death 1 (PD-1)." (PMID 35597869, 2022). "SIGLEC15, PDCD1LG2 (PD-L2), TIGIT, PDCD1 (PD-1), HAVCR2 (TIM3), CTLA4, LAG3, and CD274 (PD-L1) are transcripts related to immunological checkpoints that have a function in tumor immune evasion." (PMID 36042287, 2022). "Our results showed that the high-risk group with poor survival had a higher expression of T cell exhaustion markers, such as PDCD1/PD1, CTLA4, TIM3, LAG3, VSIR and TIGIT, which lead to tumor immune evasion." (PMID 36147509, 2022).
tumor (continued). "P2RX1 expression was significantly positively correlated with PDCD1 (r = 0.507, p = 3.84e-66), CTLA4 (r = 0.455, p = 6.07e-52) and CD274 (r = 0.351, p = 3.26e-30) in BC after adjusted by tumor purity." (PMID 35585027, 2022). "We found that the high-risk group was significantly associated with higher expression level of immune checkpoints and immune inhibitory factors, including CCL2, CTLA4, CXCR4, IL6, LAG3, PDCD1, and TGFB1, indicating tumor immune evasion." (PMID 36092894, 2022). "Immune checkpoint-related genes, including cytotoxic T-lymphocyte associated protein 4 (CTLA4), programmed cell death-ligand 1 (CD274, PD-L1), and programmed cell death 1 (CD279, PDCD1, PD-1), play vital roles in regulating tumor immune escape." (PMID 36227151, 2022). "SIGLEC15, PDCD1LG2(PD-L2), TIGIT, PDCD1(PD-1), CD274(PD-L1), CTLA4, LAG3, and HAVCR2(TIM3) are immunological checkpoints that perform a vital function in tumor immune evasion." (PMID 35840882, 2022). "Significant expressions of co-inhibitory receptors including PDCD-1, TIGIT and TIM3 were identified in immune cells, and other tumor immunity-related genes were also highly expressed." (PMID 36148946, 2022). "In a similar study, CRISPR /Cas9-mediated PDCD1 disruption increased the CD19-CAR-T cell cytotoxicity in vitro and improved CAR-T cell-mediated removal of tumor tissue in vivo in a xenograft tumor model." (PMID 36419058, 2022). "SIGLEC15, PDCD1LG2 (PD-L2), TIGIT, PDCD1 (PD-1), CD274 (PD-L1), CTLA4, LAG3, and HAVCR2 (TIM3) are transcripts related to immunological checkpoints that perform a vital function in tumor immune evasion." (PMID 36042287, 2022). "Consistent with the gene expression profile of tumor antigen-specific CD8+ T lymphocytes in human tumors, the majority of all CD8+ subsets displayed an exhausted profile with expression of Tox, Pdcd1, CTLA4, Lag3, and Havcr2." (PMID 35260537, 2022). "At the same time, in order to investigate the relationship between type and immune checkpoints, we selected genes related to tumor immune checkpoints: PD-L1, CTLA4, LAG3, PDCD1, PDCD1LG2, and TIGIT." (PMID 36105091, 2022). "PDCD1 expression was dominated by T cells, especially CD8 T cells, and increased as the tumor grade increased." (PMID 36591276, 2022). "The interaction of CD274 (PDL1) and PDCD1 (PD1) suppresses the cellular immune response of an organism, thus allowing tumor cells to evade surveillance and clearance by the immune system." (PMID 36090045, 2022). "Immune checkpoint inhibitors, such as programmed cell death 1 (PD-1)/program death-ligand 1 (PD-L1) inhibitors and cytotoxic T-lymphocyte antigen 4 (CTLA-4) destroy tumor cells through T-cell-mediated mechanisms by reversing immune escape or evasion." (PMID 36686495, 2022). "This in turn down-regulated expression of the checkpoint molecule programmed death-1 (PD-1) by repressing the Pdcd1 promoter resulting in enhanced CD8 + cytolytic T cell (CTL) function and the suppression of tumour growth and viral infections." (PMID 36104795, 2022). "Immune-stimulating signals triggered by irradiation are well known to enhance T cell infiltration into tumor tissues, and antigen-specific binding of the T-cell receptor (TCR) molecule activates the Pdcd1 gene." (PMID 36479076, 2022). "PDCD1, CD274, CTLA4, LAG3, TIGIT, and HAVCR2 are important immune checkpoints responsible for tumor immune escape." (PMID 35252356, 2022). "To evaluate the effect of both compounds on genes/proteins previously demonstrated to be important in the tumor–macrophage interaction, we also evaluated the gene expression of CD274 (Pdcd1, PD-L1), TLR4, BMPR2 and miR-21 by RT-qPCR on the treated cell lines." (PMID 35053451, 2022). "The potential implication of IRFs in tumor immunity was investigated in terms of tumor-infiltrating immune cells, a pair of immune checkpoint genes (CD274 and PDCD1), and ESTIMATE-Stromal-Immune score." (PMID 35664436, 2022).